LINC00689 (long independently transcribed non-coding RNA 689)
Synonyms: STORM
Gene: Long non-coding RNA gene on chromosome 7 (159,006,492 to 159,030,195, forward strand). Ensembl gene ENSG00000231419.
Diseases named in the same sentence as LINC00689 in open-access papers:
LINC00689 is named in the same sentence as 9 diseases in open-access papers, as found by Europe PMC text mining. Sharing a sentence is not in itself a finding about the gene and the disease. The quoted sentences say what the papers report.
glioma (9 papers, 2020 to 2025). A benign or malignant brain and spinal cord tumor that arises from glial cells (astrocytes, oligodendrocytes, ependymal cells). "The expression of LINC00689 is upregulated in glioma tissues and cell lines, and it is associated with a malignant phenotype and poor prognosis in patients with glioma." (PMID 39272133, 2024). "For example, increased LINC00689 expression in glioma tissues and cell lines is associated with rapid deterioration and poor prognosis of patients." (PMID 35113786, 2022). "Moreover, LINC00689 knockdown was associated with significant inhibition of glioma tumor growth in vivo." (PMID 35071748, 2022). "However, increased LINC00689 level was associated with poor clinical features and decreased overall survival in glioma patients, and the overexpression of miR-369-3p inhibited the proliferation and migration in glioblastoma cells." (PMID 36245971, 2022). "LINC00689 acts as a ceRNA to promote PKM2 expression in glioma cells by sponging miR-338-3p, which promotes glioma cell proliferation, migration, invasion, and glycolysis." (PMID 38184562, 2024). "Then, they demonstrated experimentally that LINC00689 was highly expressed in glioma tissue and cell lines and LINC00689 expression was correlated with a larger tumor size (particularly >3 cm), poor prognosis, and a low KPS score." (PMID 35071748, 2022). "For instance, Zhan and his group reported that LINC00689 expressions were distinctly increased in glioma, and its silence suppressed the proliferation and metastasis of glioma cells via mediation of miR-526b/IGF2BP1." (PMID 35251374, 2022). "LINC00689 interacts with miR-338-3p, leading to the upregulation of pyruvate kinase M2 (PKM2) associated with the cell growth, metastasis and glycolytic switch of patient-derived glioma tissues and glioma cell lines." (PMID 34202078, 2021). "Module 9 is highly specific in the undiffNPC cluster and includes several cancer-associated long non-coding (lnc) RNA genes (CASC15, NFIA-AS2, LINC01748, LINC00689, DNAJC27-AS1, and FEZF1-AS1) that are expressed in neuroblastoma, glioma, and other cancers." (PMID 40912258, 2025). "Furthermore, LINC00689 also was recently reported to be involved in osteosarcoma progression via the miR-655/SOC18 axis and growth, metastasis and glycolysis of glioma cells by targeting miR-338-3p/PKM2 axis." (PMID 32850794, 2020).
prostate carcinoma (3 papers, 2020 to 2024). A carcinoma that arises from epithelial cells of the prostate gland. "LINC00689 involves in progression of prostate cancer by increasing CTNNB1 levels." (PMID 37025585, 2023). "This Study illustrates that LINC00689 promotes prostate cancer progression through activation of the Wnt pathway via the miR-496/CTN-NB1 axis, and thus, studying LINC0068 may provide a new direction for further treatment of prostate cancer." (PMID 39655078, 2024).
colorectal cancer (2 papers, 2022 to 2024). A primary or metastatic malignant neoplasm that affects the colon or rectum. "In colorectal cancer, a significant overexpression of LINC00689 was observed, and its dysregulation was involved in tumor growth, drug resistance, and migration through miRNA-31-5p/YAP in colorectal cancer." (PMID 35251374, 2022). "Our findings highlight a regulatory network involving KLF15, LINC00689, PTBP1, LATS2, and the YAP1/β-catenin pathway in colorectal cancer, shedding light on potential therapeutic targets for colorectal cancer therapy." (PMID 38273088, 2024).
Obesity (1 paper, 2022). Accumulation of substantial excess body fat. "Long intergenic non-protein coding RNA689 (LINC00689) has been found to be involved in various human cancers, A clinical study carried out in Northern Han Chinese individuals showed that LINC00689 was a gene related to obesity." (PMID 35071748, 2022).
cancer (7 papers, 2019 to 2025). A tumor composed of atypical neoplastic, often pleomorphic cells that invade other tissues. "When relaxing the q-value cutoff to 0.1, LINC01365, ZNF503-AS1 and LINC00689 were identified as riboSNitch-enriched, among which ZNF503-AS1 and LINC00689 were cancer-specific." (PMID 31160636, 2019). "Moreover, knockdown of LINC00689 reversed the inhibiting effects of KLF15 overexpression on cancer cell proliferation, migration, and invasion." (PMID 38273088, 2024). "Furthermore, pan-cancer assays demonstrated that ELFN1-AS1 was related to survivals in eight types of tumors (PADD, LAML, KIRP, COAD, ACC, UVM, KIRC, and UCEC), and LINC00689 was related to survivals in eight types of tumors (MESO, UVM, THYM, HNSC, BRCA, LGG, KICH, and UCS)." (PMID 35251374, 2022).
tumor (5 papers, 2021 to 2024). "We then observed that injection of CRC cells overexpressed KLF15 increased the expression of KLF15 and LINC00689 in tumor tissues, while decreased YAP1 and β-catenin levels." (PMID 38273088, 2024). "Furthermore, overexpression of LINC00689 repressed the proliferative, migratory, and invasive capacities of tumor cells, and N-cadherin level in vitro." (PMID 38273088, 2024).
LINC00689 also shares sentences with these, for which no sentence is quoted: glioblastoma (1 paper); neuroblastoma (1); osteosarcoma (1).